PPP3CC (protein phosphatase 3 catalytic subunit gamma)
Description:
Calcium-dependent, calmodulin-stimulated protein phosphatase which plays an essential role in the transduction of intracellular Ca(2+)-mediated signals. Dephosphorylates and activates transcription factor NFATC1. Dephosphorylates and inactivates transcription factor ELK1. Dephosphorylates DARPP32.
Synonyms: CALNA3; CNA3; PP2Bgamma
Tractability: Small molecule: a structure with a bound ligand is known. PROTAC: ubiquitination databases record sites on it; its protein half-life has been measured.
Gene: Protein-coding gene on chromosome 8 (22,440,819 to 22,541,145, forward strand). Ensembl gene ENSG00000120910.
Subcellular location: Mitochondrion
Subcellular location (Human Protein Atlas): Cytosol; Calyx; Nucleoplasm
Pathways (Reactome):
Programmed Cell Death: Activation of BAD and translocation to mitochondria
Signal Transduction: DARPP-32 events
Gene Ontology:
Molecular function: calcium-dependent protein serine/threonine phosphatase activity; calmodulin-dependent protein phosphatase activity; protein binding; protein serine/threonine phosphatase activity; calmodulin binding; hydrolase activity
Biological process: calcineurin-NFAT signaling cascade; protein dephosphorylation; calcineurin-mediated signaling; negative regulation of calcium ion import across plasma membrane; positive regulation of calcineurin-NFAT signaling cascade; positive regulation of calcium ion import across plasma membrane; positive regulation of synaptic vesicle endocytosis; regulation of synaptic vesicle endocytosis
Cellular component: cytoplasm; calcineurin complex; cytosol; mitochondrion; protein serine/threonine phosphatase complex; glutamatergic synapse; presynapse
Genetic constraint (gnomAD): Loss-of-function variants: 26 observed, 46.96 expected, observed/expected ratio (o/e) 0.55, 90% interval 0.41 to 0.77. The upper end of that interval is the gene's LOEUF score, 0.77, which puts it in group 3 of 6, group 1 being the genes least tolerant of losing a copy. Missense variants: 525 observed, 584.69 expected, observed/expected ratio (o/e) 0.9, 90% interval 0.83 to 0.96. Synonymous variants: 184 observed, 209.15 expected, observed/expected ratio (o/e) 0.88, 90% interval 0.78 to 0.99.
Homologues: Orthologues: chimpanzee PPP3CC (99% identical), macaque PPP3CC (99% identical), rabbit PPP3CC (92% identical), pig PPP3CC (91% identical), guinea pig PPP3CC (88% identical), mouse Ppp3cc (87% identical), rat Ppp3cc (86% identical), tropical clawed frog ppp3cb (80% identical), zebrafish ppp3ccb (80% identical), dog PPP3CC (74% identical), Drosophila melanogaster Pp2B-14D (74% identical), Drosophila melanogaster CanA-14F (73% identical), and 2 more. Paralogues in human: PPP3CB (80% identical), PPP3CA (80% identical), PPEF2 (26% identical), PPP1CA (25% identical), PPP1CC (25% identical), PPP1CB (24% identical), PPP2CA (24% identical), PPP2CB (24% identical), PPP4C (24% identical), PPEF1 (23% identical), PPP5C (23% identical), PPP6C (22% identical).
Diseases named in the same sentence as PPP3CC in open-access papers:
PPP3CC is named in the same sentence as 25 diseases in open-access papers, as found by Europe PMC text mining. Sharing a sentence is not in itself a finding about the gene and the disease. The quoted sentences say what the papers report.
schizophrenia (15 papers, 2008 to 2024). A major psychotic disorder characterized by abnormalities in the perception or expression of reality. "Of the five human PP3 genes, one is implicated in genetic disease: PPP3CA (OMIM#618265, #617711), while PPP3CC is linked to schizophrenia susceptibility." (PMID 36313552, 2022). "Several independent studies performed linkage analysis where they identified PPP3CC as a susceptibility locus for schizophrenia." (PMID 36313552, 2022). "Another study using forebrain-specific PPP3CC gene-knockout mice reported multiple abnormal behaviors associated with schizophrenia, such as decreased social interaction and impairments in prepulse inhibition." (PMID 31619735, 2019). "Subsequently the protein phosphatase calcineurin (CN) was identified as a schizophrenia candidate protein based on the phenotype of CN−/− mice, and the association of the gene encoding one of its subunits (PPP3CC) with schizophrenia in a Japanese population." (PMID 29520222, 2018). "Human genetic studies have identified associations between variations in PPP3CC, the gene that encodes the α-1 subunit of calcineurin A, and schizophrenia, in both Caucasian and Asian populations." (PMID 29520222, 2018). "The ppp3cc gene is a gene linked to susceptibility to schizophrenia, and it has been reported that the ppp3cc gene is also associated with prostate cancer." (PMID 28700704, 2017). "Recently, genetic association between schizophrenia and genetic variation of the human calcineurin A gamma subunit gene (PPP3CC) has been reported." (PMID 18201382, 2008). "Most importantly, Gerber and collaborators reported the association of schizophrenia with genetic variation of the PPP3CC gene, which encodes the CNA-γ-subunit in a Caucasian population." (PMID 18201382, 2008). "The PPP3CC catalytic subunit of calcineurin is located at 8p21, a highly replicated schizophrenia susceptibility locus, and variants within the gene are associated with schizophrenia." (PMID 18201382, 2008). "In particular, the polymorphism of protein phosphatase 3 catalytic subunit gamma (PPP3CC), a gene encoding the CaN γ-catalytic subunit, was previously found to be relevant to schizophrenia." (PMID 31619735, 2019). "These include NOS1, AKT1, DTNBP1, DNMT1, PPP3CC and SOX10, which have previously been associated with schizophrenia." (PMID 24399042, 2014). "The secondary analyses instead confirmed effects of the DAO, PPP3CC, and DTNBP1 genes on schizophrenia susceptibility; these effects were mediated not only by the gender and paranoid/non-paranoid dichotomy but also by epistatic/interaction mechanisms." (PMID 23497497, 2013). "PPP3CC (encoding calcineurin catalytic γ subunit) is located very close to EGR3 on chromosome 8 and was reported to be associated with schizophrenia." (PMID 20156358, 2010). "For example, we demonstrated that GAD, protein phosphatase 3 catalytic subunit gamma (PPP3CC) and glutamate ionotropic receptor NMDA type subunit (GRIN) were susceptible to tissue pH and RIN, all of which were associated with schizophrenia in previous postmortem brain studies." (PMID 37520228, 2023). "Although the results are preliminary and needed replication in a larger sample, this study suggests that NMDA receptor-mediated signalling genes (DAO, PPP3CC, DTNBP1) might be involved in schizophrenia pathogenic mechanisms related to gender." (PMID 23497497, 2013). "The discrepancies between the primary and the secondary analyses may be reconciled assuming that the DAO, PPP3CC, and DTNBP1 genes modulate the susceptibility for schizophrenia only under definite circumstances." (PMID 23497497, 2013). "In particular DAO, PPP3CC, and DTNBP1, might be differentially involved in schizophrenia susceptibility according to gender and gene interaction mechanisms." (PMID 23497497, 2013). "The primary analyses did not demonstrate associations between schizophrenia and any of the 32 studied DAOA, DAO, PPP3CC, and DTNBP1 SNPs." (PMID 23497497, 2013).
glioma (6 papers, 2018 to 2024). A benign or malignant brain and spinal cord tumor that arises from glial cells (astrocytes, oligodendrocytes, ependymal cells). "Similarly, in glioma cell lines, PPP3CC downregulation was associated with tumor progression." (PMID 34573382, 2021). "PPP3CC decrease is responsible for activation of NF-κB and contributes to invasion and growth in glioma cells." (PMID 31086232, 2019). "Another set of experiments showed that the repression of PPP3CC correlated with glioma progression and was often decreased in gliomas." (PMID 32309604, 2018). "PPP3CC repression has been reported to contribute to invasion and growth of glioma cells." (PMID 38475971, 2024). "Suppression of PPP3CC by ZEB1 contributes to nuclear factor‐kappa B activation and promotes the growth and invasion of glioma cells." (PMID 34739189, 2022).
prostate carcinoma (5 papers, 2017 to 2021). A carcinoma that arises from epithelial cells of the prostate gland. "A decrease in PPP3CC expression was associated with the recurrence of prostate cancer." (PMID 33392087, 2020). "PPP3CC, protein phosphatase 3 catalytic subunit gamma was a shared gene in these two pathways, decreased PPP3CC has been found in prostate cancer and gliomas." (PMID 29991755, 2018). "Among the isoforms encoding for the CN subunits, PPP3CC, also called CNA3, CALNA3, or PP2Bgamma, has been shown to be involved in apoptosis in bladder cancer, and reduced expression was significantly correlated to prostate cancer recurrence." (PMID 34573382, 2021).
male infertility (3 papers, 2016 to 2025). The inability of the male to effect fertilization of an ovum after a specified period of unprotected intercourse. "Sperm-specific calcineurin consists of a catalytic subunit (PPP3CC) and a regulatory subunit (PPP3R2), and the deletion of PPP3CC/PPP3R2 resulted in male infertility due to an inflexible mid-piece of sperm in mice." (PMID 41428164, 2025). "Specifically, the knockout of PPP3CC in mice reduced the sperm motility and leads to male infertility." (PMID 37048090, 2023). "Next, to clarify the specific contribution of FKBP12.6 in FK506-induced male infertility, we prepared several tagged proteins including GST-tagged FKBP12, GST-tagged FKBP12.6, His-tagged PPP3CC, and His-tagged PPP3R2, for conducting the pull-down experiments." (PMID 41428164, 2025).
bladder cancer (1 paper, 2021). "In addition, there are very few studies reporting that PPP3CC functions as an oncosuppressor in castration-resistant prostate cancer (CRPC) and in bladder cancer, but there is no information about its role in OC." (PMID 34573382, 2021).
breast carcinoma (1 paper, 2022). "PPP2CB, PPP3CA, PPP3CB, PPP3CC and PPP6C were significantly expressed at lower levels in breast cancer tissues." (PMID 34964699, 2022). "In the Oncomine database, when compared with normal breast tissues, PPP1CA, PPP2CA, PPP4C and PPEF1 were significantly elevated in breast cancer tissues, while PPP1CB, PPP2CB, PPP3CA, PPP3CB, PPP3CC and PPP6C were significantly decreased in breast cancer tissues." (PMID 34964699, 2022).
colorectal cancer (1 paper, 2024). A primary or metastatic malignant neoplasm that affects the colon or rectum. "For example, an epimutation was detected at the promoter of PPP3CC (Protein Phosphatase 3 Catalytic Subunit Gamma) in 1 individual (colorectal cancer)." (PMID 38475971, 2024).
failure of heart (1 paper, 2020). "MTOR, EP300 and PPP3CC in the Senescence Pathway were also involved in failure of heart." (PMID 32423033, 2020).
lung adenocarcinoma (1 paper, 2024). A carcinoma that arises from the lung and is characterized by the presence of malignant glandular epithelial cells. "As GADD45B and PPP3CC are activated by shikonin to suppress cell proliferation and metastasis in lung adenocarcinoma, we speculated whether their expression was correlated with patient prognosis." (PMID 38167059, 2024). "Therefore, we preferentially selected GADD45B and PPP3CC as candidate targets for shikonin in lung adenocarcinoma cells." (PMID 38167059, 2024). "Taken together, all these results demonstrated that both GADD45B and PPP3CC were downregulated in lung adenocarcinoma as TSGs and could be activated by shikonin through the MAPK signaling pathway." (PMID 38167059, 2024). "Interestingly, among these selected TSGs, GADD45B and PPP3CC have been reported as tumor suppressors that inhibit cancer cell proliferation and invasion in various cancers; however, their roles in lung adenocarcinoma remain unknown." (PMID 38167059, 2024). "The expression of both GADD45B and PPP3CC was remarkably downregulated in lung adenocarcinoma, as well as in numerous other cancer types, in line with the reported downregulation of GADD45B and PPP3CC in various cancers." (PMID 38167059, 2024). "The expression of both GADD45B and PPP3CC was not related to gender, that is, no matter what gender is, their expressions were distinctly lower in lung adenocarcinoma than those of normal ones." (PMID 38167059, 2024).
osteosarcoma (1 paper, 2023). A usually aggressive malignant bone-forming mesenchymal neoplasm, predominantly affecting adolescents and young adults. "Moreover, AC037459.2 might act jointly with PPP3CC, a neighboring gene, to be involved with osteosarcoma and further cancers by regulating apoptosis and the MAPK signaling pathway, with the need for further research, as the authors themselves stated." (PMID 37182169, 2023).
renal dysfunction (1 paper, 2021). "The odds of renal dysfunction were higher in variant carriers of PPP3CC rs10108011, PPP3CC rs2461494, and PRKAG2 rs7805747, whereas the odds of renal dysfunction were lower in variant carriers of CACNA1D rs893365 and NR3C2 rs1490453." (PMID 33868389, 2021).
renal tumour (1 paper, 2017). "CNAs of suppressor genes present in at least 5 renal tumour genomes linked PPP3CC, PPP2CB and RBX1 in 9/11/7 HRO tumours with 19/11/11 KEGG pathways." (PMID 28486536, 2017).
retinal degeneration (1 paper, 2011). Degeneration of the retina. "As PPP3CC participates in TAU homeostasis, its decrease during retinal degeneration, either due to inherited condition (rd1) or to retinal detachment (RD), may induce TAU hyperphosphorylation and further accelerate neuronal death through TAU fibrillization." (PMID 22174898, 2011).
cancer (7 papers, 2014 to 2025). A tumor composed of atypical neoplastic, often pleomorphic cells that invade other tissues. "Elevated levels of calcineurin and mutations in the gene PPP3CC are common occurrences in many cancers, resulting in elevated anti-apoptotic factors that directly enhance the transcriptional and translational events required for cancer metastasis." (PMID 40725140, 2025). "In this study, we supposed that CMTM3 may be a gene of Wnt signaling pathways and associated to some pathways in cancer progression along with CCND3, PPP3CA, and PPP3CC." (PMID 34475993, 2021). "The nine mRNAs are coding for proteins involved in cell cycle regulation (CDCA7L), modification of the T cell and B cell immune response (GBP2, GLUL, HERC5, PPP3CC), erythropoiesis (GBP2), and cell migration of cancer and hematopoietic cells (HERC5, HMHA1)." (PMID 28236054, 2017). "Taken together, these results suggested that shikonin might affect the expression of GADD45B and PPP3CC through the JNK/P38/MAPK pathway, therefore exerting an inhibitory effect on the proliferation and migration of cancer cells." (PMID 38167059, 2024).
tumor (6 papers, 2017 to 2025). "In vitro regulation of PPP3CC expression through miR-200c-3p and RNA interference technology led to a concomitant modulation of BCL2- and p-AKT-related pathways, suggesting the tumor suppressive role of PPP3CC in EOC." (PMID 34573382, 2021). "The increased capacity of UWB 1.289 + BRCA1 to form colonies and the ability to migrate after K.D. of PPP3CC supports the hypothesis of its function as a tumor suppressor." (PMID 34573382, 2021). "Moreover, it would be interesting to evaluate the tumor suppressor role of PPP3CC through the NFκB pathway as demonstrated in CRPC." (PMID 34573382, 2021). "Patients with LUAD with higher levels of expression of GADD45B and PPP3CC exhibited better survival outcomes, suggesting that GADD45B and PPP3CC indeed exhibit a tumor-suppressive effect." (PMID 38167059, 2024). "The remaining six genes (e.g., PPP3CC, ITGA5, ITK, CDC25B, CCND2, and THY1) were expressed at higher levels in CD45+ TAS as compared to CD45+ tumor." (PMID 36230846, 2022).
infectious disease (1 paper, 2010). A disorder directly resulting from the presence and activity of a microbial, viral, or parasitic agent in humans. "We observed that top functions these genes involved are RNA post-Transcriptional Modification (CLP1 TSEN2 and TSEN54) and infectious disease and inflammatory disease (NR3C1, PPP3CC, and PPP3R1)." (PMID 21172007, 2010).
PPP3CC also shares sentences with these, for which no sentence is quoted: bipolar affective disorder (2 papers); depression (2); epilepsy (1); Epithelial Ovarian Cancer (1); hepatocellular carcinoma (1); Infertility (1); lupus (1); pancreatic adenocarcinoma (1); retinal detachment (1).